HELB (DNA helicase B)
Description:
5'-3' DNA helicase involved in DNA damage response by acting as an inhibitor of DNA end resection. Recruitment to single-stranded DNA (ssDNA) following DNA damage leads to inhibit the nucleases catalyzing resection, such as EXO1, BLM and DNA2, possibly via the 5'-3' ssDNA translocase activity of HELB. As cells approach S phase, DNA end resection is promoted by the nuclear export of HELB following phosphorylation. Acts independently of TP53BP1. Unwinds duplex DNA with 5'-3' polarity. Has single-strand DNA-dependent ATPase and DNA helicase activities. Prefers ATP and dATP as substrates. During S phase, may facilitate cellular recovery from replication stress.
Synonyms: hDHB; DHB
Tractability: PROTAC: ubiquitination databases record sites on it; its protein half-life has been measured.
Gene: Protein-coding gene on chromosome 12 (66,302,493 to 66,343,643, forward strand). Ensembl gene ENSG00000127311.
Subcellular location: Nucleus; Cytoplasm; Chromosome
Subcellular location (Human Protein Atlas): Nucleoplasm; Cytosol; Mitochondria; Nuclear bodies
Gene Ontology:
Molecular function: 5'-3' DNA helicase activity; ATP hydrolysis activity; protein-containing complex binding; single-stranded DNA helicase activity; DNA helicase activity
Biological process: DNA damage response; DNA replication; DNA replication, synthesis of primer; negative regulation of double-strand break repair via homologous recombination; regulation of DNA double-strand break processing; DNA-templated DNA replication
Cellular component: chromosome; cytoplasm; cytosol; DNA replication factor A complex; nuclear body; nucleoplasm; nucleus; site of double-strand break
Genetic constraint (gnomAD): Loss-of-function variants: 68 observed, 72.53 expected, observed/expected ratio (o/e) 0.94, 90% interval 0.77 to 1.15. The upper end of that interval is the gene's LOEUF score, 1.15, which puts it in group 5 of 6, group 1 being the genes least tolerant of losing a copy. Missense variants: 933 observed, 1,056.8 expected, observed/expected ratio (o/e) 0.88, 90% interval 0.84 to 0.93. Synonymous variants: 360 observed, 388.01 expected, observed/expected ratio (o/e) 0.93, 90% interval 0.85 to 1.01.
Homologues: Orthologues: chimpanzee HELB (99% identical), macaque HELB (95% identical), rabbit HELB (74% identical), dog HELB (71% identical), pig HELB (70% identical), guinea pig HELB (69% identical), mouse Helb (65% identical), rat Helb (65% identical), tropical clawed frog helb (40% identical), zebrafish helb (36% identical). Paralogues in human: YTHDC2 (13% identical), DHX29 (12% identical), DHX34 (12% identical), TDRD9 (12% identical), DHX57 (12% identical), DHX37 (12% identical), DHX8 (11% identical), DHX35 (11% identical), DHX9 (11% identical), DHX36 (11% identical), DHX38 (11% identical), DHX16 (11% identical), and 6 more.
Diseases named in the same sentence as HELB in open-access papers:
HELB is named in the same sentence as 15 diseases in open-access papers, as found by Europe PMC text mining. Sharing a sentence is not in itself a finding about the gene and the disease. The quoted sentences say what the papers report.
mammary tumor (2 papers, 2020 to 2025). "Knockdown of HELB in BRCA1-deficient mammary tumor cells results in resistance to PARPi, which suggests that BRCA1-independent HR is activated in the absence of HELB." (PMID 32455610, 2020).
epilepsy (1 paper, 2014). A brain disorder characterized by episodes of abnormally increased neuronal discharge resulting in transient episodes of sensory or motor neurological dysfunction, or psychic dysfunction. "HELB Asp506 is thus particularly interesting for further assessment of a role in epilepsy." (PMID 24795746, 2014).
ovarian carcinoma (1 paper, 2025). A malignant neoplasm originating from the surface ovarian epithelium. "We have confirmed the histotype-specific associations of rare protein-truncating variants in the known epithelial ovarian cancer susceptibility genes and found a novel association for protein-truncating variants in HELB with risk of non-mucinous, non-high grade serous ovarian cancer." (PMID 39939714, 2025).
Premature ovarian insufficiency (1 paper, 2025). Amenorrhea due to loss of ovarian function before the age of 40. "HELB is involved in regulating female reproductive aging and genetic variants in HELB contribute to premature ovarian insufficiency and early age of natural menopause." (PMID 41212051, 2025).
Sepsis (1 paper, 2025). Sepsis is defined as life-threatening organ dysfunction caused by a dysregulated host response to infection. "A lactylation-based prognostic model was developed, comprising eight key genes (CD160, HELB, ING4, PIP5K1C, SRPRA, CDCA7, FAM3A, PPP1R15A), and demonstrated strong predictive performance for sepsis outcomes (AUC = 0.78 in the training cohort; AUC = 0.73 in the validation cohort)." (PMID 40612938, 2025). "Ultimately, 8 key genes were identified: CD160, HELB, ING4, PIP5K1C, SRPRA (HR < 1); and CDCA7, FAM3A, PPP1R15A (HR > 1), and the hub genes showed apparent differences in expression between alive and dead sepsis patients." (PMID 40612938, 2025).
skin pigmentation disorder (1 paper, 2020). A pigmentation disease that involves the zone of skin. "Non-synonymous mutations in HELB have been associated with male and female reproductive traits in tropical cattle and with Xeroderma pigmentosum, complementation group B, a skin pigmentation disorder in humans leading to solar hypersensitivity of the skin." (PMID 32460767, 2020).
tumor (2 papers, 2017 to 2025). "The observation that HELB-depleted BRCA1-deficient tumor cells were resistant to a PARP inhibitor is consistent with an auto-regulatory mechanism to limit end-resection dependent on HELB and its interaction with RPA." (PMID 28594346, 2017).
HELB also shares sentences with these, for which no sentence is quoted: Anxiety (3 papers); colorectal cancer (1); depression (1); endometrioid ovarian cancer (1); infection (1); osteosarcoma (1); serous ovarian cancer (1); xeroderma pigmentosum (1).